ACTB (actin beta)
Description:
Actin is a highly conserved protein that polymerizes to produce filaments that form cross-linked networks in the cytoplasm of cells. Actin exists in both monomeric (G-actin) and polymeric (F-actin) forms, both forms playing key functions, such as cell motility and contraction. In addition to their role in the cytoplasmic cytoskeleton, G- and F-actin also localize in the nucleus, and regulate gene transcription and motility and repair of damaged DNA. Plays a role in the assembly of the gamma-tubulin ring complex (gTuRC), which regulates the minus-end nucleation of alpha-beta tubulin heterodimers that grow into microtubule protafilaments. Part of the ACTR1A/ACTB filament around which the dynactin complex is built (By similarity). The dynactin multiprotein complex activates the molecular motor dynein for ultra-processive transport along microtubules (By similarity).
Synonyms: BKRNS; BNS; BRWS1; CSMH; DDS1; PS1TP5BP1; THC8
Tractability: Small molecule: a structure with a bound ligand is known. Antibody: its Gene Ontology location is reachable by antibodies, with high confidence. PROTAC: UniProt records ubiquitination sites on it; ubiquitination databases record sites on it; its protein half-life has been measured.
Target class: Other cytosolic protein
Gene: Protein-coding gene on chromosome 7 (5,526,409 to 5,563,902, reverse strand). Ensembl gene ENSG00000075624.
Subcellular location: Cytoplasm, cytoskeleton; Nucleus
Pathways (Reactome):
Disease: FCGR3A-mediated phagocytosis; Paradoxical activation of RAF signaling by kinase inactive BRAF; Signaling by BRAF and RAF1 fusions; Signaling by RAF1 mutants; Signaling by high-kinase activity BRAF mutants; Signaling by moderate kinase activity BRAF mutants; Signaling downstream of RAS mutants
Chromatin organization: Formation of neuronal progenitor and neuronal BAF (npBAF and nBAF); Formation of the canonical BAF (cBAF) complex; Formation of the embryonic stem cell BAF (esBAF) complex; Formation of the non-canonical BAF (ncBAF) complex; Formation of the polybromo-BAF (pBAF) complex; HATs acetylate histones
Signal Transduction: MAP2K and MAPK activation; RHO GTPases Activate Formins; RHO GTPases Activate WASPs and WAVEs; RHO GTPases activate IQGAPs; RHOF GTPase cycle; VEGFA-VEGFR2 Pathway
Developmental Biology: EPH-ephrin mediated repulsion of cells; EPHB-mediated forward signaling; Interaction between L1 and Ankyrins; Recycling pathway of L1; Regulation of MITF-M-dependent genes involved in pigmentation
Cell-Cell communication: Activation of STAT3 by cadherin engagement; Adherens junctions interactions; Cell-extracellular matrix interactions; Regulation of CDH1 Function
Vesicle-mediated transport: Clathrin-mediated endocytosis; Formation of annular gap junctions; Gap junction degradation; Translocation of SLC2A4 (GLUT4) to the plasma membrane
Metabolism of proteins: Folding of actin by CCT/TriC; Prefoldin mediated transfer of substrate to CCT/TriC; UCH proteinases
Gene expression (Transcription): B-WICH complex positively regulates rRNA expression; Regulation of endogenous retroelements by Piwi-interacting RNAs (piRNAs)
Immune System: GBP-mediated host defense; Regulation of actin dynamics for phagocytic cup formation
Sensory Perception: Sensory processing of sound by inner hair cells of the cochlea
and 4 more pathways
Gene Ontology:
Molecular function: ATP hydrolysis activity; identical protein binding; kinesin binding; nitric-oxide synthase binding; nitric-oxide synthase regulator activity; nucleosomal DNA binding; protein binding; protein kinase binding; structural constituent of postsynaptic actin cytoskeleton; Tat protein binding; transporter regulator activity; structural constituent of cytoskeleton; tau protein binding
Biological process: adherens junction assembly; apical protein localization; cell motility; cellular response to cytochalasin B; chromatin remodeling; establishment or maintenance of cell polarity; morphogenesis of a polarized epithelium; platelet aggregation; positive regulation of double-strand break repair via homologous recombination; protein localization to adherens junction; regulation of cell cycle; regulation of norepinephrine uptake; regulation of protein localization to plasma membrane; regulation of transepithelial transport; substantia nigra development; axonogenesis; cytoskeleton organization; maintenance of blood-brain barrier; microtubule nucleation; negative regulation of cell differentiation; positive regulation of cell differentiation; positive regulation of cell population proliferation; positive regulation of DNA-templated transcription; positive regulation of double-strand break repair; positive regulation of myoblast differentiation; and 12 more
Cellular component: actin cytoskeleton; adherens junction; apical junction complex; blood microparticle; cell-cell junction; chromatin; cytoplasm; cytoplasmic ribonucleoprotein granule; cytoskeleton; extracellular exosome; extracellular region; focal adhesion; glutamatergic synapse; lamellipodium; membrane; NuA4 histone acetyltransferase complex; nucleosome; nucleus; postsynaptic actin cytoskeleton; protein-containing complex; ribonucleoprotein complex; tight junction; vesicle; actin filament; axon; and 20 more
Genetic constraint (gnomAD): Loss-of-function variants: 2 observed, 32.56 expected, observed/expected ratio (o/e) 0.0614, 90% interval 0.024 to 0.19. The synonymous counts are far from expectation, so gnomAD's model fits this gene poorly and the ratio says little. Missense variants: 56 observed, 549.95 expected, observed/expected ratio (o/e) 0.1, 90% interval 0.081 to 0.13. Synonymous variants: 335 observed, 223.93 expected, observed/expected ratio (o/e) 1.5, 90% interval 1.37 to 1.64.
Gene-disease validity (ClinGen):
ClinGen rates the evidence that ACTB causes each of these diseases.
Baraitser-Winter cerebrofrontofacial syndrome (autosomal dominant): Definitive.
ACTB-associated syndromic thrombocytopenia (autosomal dominant): Moderate. A syndrome associated with developmental delay, mild intellectual disability, microcephaly, and thrombocytopenia with platelet anisotropy and enlarged platelets.
Homologues: Orthologues: chimpanzee ACTB (100% identical), guinea pig ACTB (100% identical), mouse Actb (100% identical), pig ACTB (100% identical), rat Potef (100% identical), tropical clawed frog actb (99% identical), macaque ACTB (99% identical), dog ACTB (89% identical), rabbit ACTG1 (61% identical). Paralogues in human: ACTG1 (99% identical), ACTC1 (94% identical), ACTA1 (94% identical), ACTA2 (94% identical), ACTG2 (93% identical), ACTBL2 (91% identical), ACTR1B (55% identical), ACTR1A (54% identical), ACTRT3 (49% identical), ACTR2 (49% identical), ACTRT2 (49% identical), ACTRT1 (49% identical), and 14 more.
Diseases named in the same sentence as ACTB in open-access papers:
ACTB is named in the same sentence as 262 diseases in open-access papers, as found by Europe PMC text mining. Sharing a sentence is not in itself a finding about the gene and the disease. The quoted sentences say what the papers report.
breast carcinoma (35 papers, 2007 to 2025). "Analysis of ACTB expression based on The Cancer Genome Atlas (TCGA) database showed abnormal expression of ACTB in breast cancer cases with mutation or amplification of ACTB." (PMID 39070120, 2023). "In addition, SETD3 regulates the expression of multiple breast-cancer-associated genes, such as ACTB, FBXW7, Fascin, eNOS, and MMP-2, which suggests it as a promising biomarker for breast cancer prognosis." (PMID 35912180, 2022). "However, GAPDH and TBP in hepatic cancer cell lines and ACTB and B2M in breast cancer cell lines have M values > 1, which causes us to consider them as unstable reference genes." (PMID 34752497, 2021). "ACTB was expressed most highly among the breast cancer cell lines, but also showed greatest variation between biological replicates ranging from 8 ng / μl to 202 ng / μl in MCF-7 cells, and 30 ng / μl to 179 ng / μl in T-47D cells." (PMID 39838295, 2025). "First, ACTB-Ribo(4A)−590 was evaluated in comparison vs. untransfected control cells for U-2 OS cells, HeLa cells, and the breast cancer model cell line MDA-MB231." (PMID 36797241, 2023). "A high abundance of ACTB was correlated with cell proliferation of breast cancer cell lines in one study." (PMID 35765478, 2022). "PPIA along with ACTB was found to be the most stable reference gene for basal type breast cancer cell lines in hypoxic and serum deprived conditions." (PMID 34681026, 2021). "ACTB, another widely used reference gene, has also been previously verified as a candidate stable reference gene for breast cancer tissue and normal tissues." (PMID 32977762, 2020). "They further reported that RNA18S and ACTB were the best pair of genes across all breast cancer cell lines." (PMID 32977762, 2020). "LongGF also detected more potential novel gene fusions (ACTB:H3F3B, SLC25A24:NBPF6, STMN1:ACTG1), and these genes were reported to be associated with breast cancer." (PMID 33372596, 2020). "On the contrary, ACTB has been found among the most stably expressed HKG in breast cancer cell lines." (PMID 27339468, 2016). "For normalization of cells without transfection treatments, 18S rRNA and ACTB would be appropriate across all cells, and GAPDH and ACTB would be appropriate in basal breast cancer cells." (PMID 25617865, 2015). "Both 18S rRNA and ACTB have been suggested to be suitable for normalization among a set of human breast cancer cell lines of increasing metastatic potential, but limitations do exist." (PMID 25617865, 2015). "We have validated two genes, 18S rRNA and ACTB as control genes for RT-qPCR analysis of human breast cancer cell lines containing different subtypes using 4 different mathematical approaches." (PMID 25617865, 2015). "GAPDH and ACTB were among the least and the most stable genes which a in concordance with other breast cancer studies." (PMID 21702980, 2011). "Another important finding is that some of the commonly used control genes in breast cancer (ACTB and TFRC) appear to be less stable than previously assumed." (PMID 19187545, 2009). "A few of NETs-related genes are highly expressed in breast cancer, such as ACTB, ACTG1, KRT10." (PMID 37304069, 2023). "That study also showed that ACTB expression in invasive breast carcinoma tissue was higher than that in normal tissue and that there was a relationship between high ACTB expression and poor prognosis in breast cancer." (PMID 39070120, 2023). "ACTB expression was observed higher in cervical cancer, head and neck cancer, leukemia, lymphoma and pancreatic cancer compared with normal tissues, and lower in breast cancer, lung cancer, ovarian cancer and prostate cancer." (PMID 34486492, 2021). "In addition, GUSB, TUBA1A, RPL13A, and B2M, which previous studies suggested being stable RGs in breast cancer research, and two classical RGs, ACTB and GAPDH, were also considered." (PMID 34895237, 2021). "ACTB proved to be the best housekeeper to analyze gene expression in canine mammary tumors." (PMID 27187374, 2016).
breast carcinoma (continued). "However, ACTB has been reported to play a role in the migration, motility, and invasion of mammary epithelial cells including breast cancer cells." (PMID 23049944, 2012). "TFRC and ACTB were verified as the best combination of two genes for breast cancer quantification." (PMID 21702980, 2011). "Many of these are enzymes or cytoskeletal proteins (ANXA1, KRT10, KRT16, TUBB, ACTB, ACTA1, PKM2, and HSPA8) that have been previously reported as able to induce autoantibodies with diagnostic potential across different tumor types, including PDAC, breast cancer, and neuroblastoma." (PMID 30651550, 2019). "Disrupted expression of core circadian genes (BMAL1, CLOCK and PER3) and hub genes such as ACTB, GAPDH and CDK1 suggests that circadian gene dysregulation promotes breast cancer progression and represents a potential therapeutic target." (PMID 41908013, 2025). "The total score of all algorithms combined was lowest for ACTB, followed by RPL13a and GAPDH, making these genes the most stable ones in the combined data set in the breast cancer cell lines studied." (PMID 40133575, 2025). "In the breast cancer cell group THRAP3, RHOA, and QRICH1 were the top three stably expressed genes, while B2M, TUBA1A, and ACTB were the least stably expressed genes." (PMID 34895237, 2021). "In the breast cancer cell group, THRAP3, DNAJC8, and RPL13A were the three most stably expressed genes, while TUBA1A, B2M, and ACTB were the least stably expressed genes." (PMID 34895237, 2021). "The efficiency and specificity of these primers except hypoxanthine phosphoribosyltransferase 1 (HPRT1), TATA-box binding protein (TBP), and actin beta (ACTB) were also studied in exosomal RNA of hepatic and breast cancer cell lines by our team recently." (PMID 34752497, 2021). "In the breast cancer cell line group, THRAP3, RHOA, and QRICH1 were the three most stably expressed genes, while B2M, ACTB, and TUBA1A were the least stably expressed genes." (PMID 34895237, 2021). "In the breast cancer tissue group DNAJC8, RPL13A, and TARDBP were the most stably expressed genes, while ACTB, B2M, and GAPDH were the least stably expressed genes." (PMID 34895237, 2021). "There is a marked difference in ADHFE1 expression among breast cancer cells, although overall expression levels of ADHFE1 are rather low compared to housekeeping genes PPIA and ACTB." (PMID 33916579, 2021). "Our results overally indicated that GAPDH, YWHAZ, and UBC were the most stable reference genes in breast cancer cell lines, including MCF7, SKBR3 and MDA-MB231, and B2M and ACTB were the least stable ones." (PMID 34752497, 2021). "For all breast cancer tissue and cell line samples, THRAP3, RHOA, QRICH1 were the most stably expressed genes, and TUBA1A, B2M, ACTB were the least stably expressed RGs." (PMID 34895237, 2021). "Various other reference genes in the past have been described to be suitable reference genes in breast cancers including GAPDH, ACTB, PPIA and RNA28S/RNA18S." (PMID 34681026, 2021). "A stability analysis suggests that 18S rRNA-ACTB is the best reference gene combination across all cell lines; ACTB-GAPDH is best for basal breast cancer cell lines; and HSPCB-ACTB is best for ER+ breast cancer cells." (PMID 25617865, 2015). "We thus performed correlation analysis between the 6 actin genes (ACTA1, ACTA2, ACTB, ACTC1, ACTG1, and ACTG2) 18 and the ABPs involved in translocation/polymerization and transcriptional regulation of nuclear actin in breast cancer through the GEPIA2 web-based platform." (PMID 39308680, 2024). "Interestingly, we observed that one set of proteins was identified more frequently, with HLA-A, HLA-B, A2M, ACTB, ALDOA, ANXA2, and FN1 identified in at least 13 of 22 studies that explored the vesicular proteome in breast cancer." (PMID 37629204, 2023). "In addition, THRAP3, TARDBP, and YY1 were the most stably expressed genes in the breast cancer cell lines, while B2M, TUBA1A, and ACTB were the least stably expressed genes." (PMID 34895237, 2021).
breast carcinoma (continued). "Although ACTB siRNA inhibited colony growth in both cell lines tested in this study, we found that it affected some, but not all, breast cancer patient cells when tested on the CBCS (manuscript in preparation)." (PMID 23049944, 2012). "However, ACTB was shown to not be a suitable reference gene in a study comprising three breast cancer cell lines and in another study involving only MCF-7 cells." (PMID 40133575, 2025). "Therefore, to confirm the roles of these genes on the vital regulatory mechanisms in breast cancer, we compared the potential role of novel RGs (SF1, TRA2B, THRAP3, RHOA, and QRICH1) vs. traditional RGs (ACTB, and GAPDH) in the normalization of target gene expression." (PMID 34895237, 2021). "On the basis of our findings, we suggest that TFRC is the most stable EC, ACTB and TFRC is the best combination of two reference genes to quantify uPA, and that using RPLP0 and GAPDH are not recommendable for breast cancer." (PMID 21702980, 2011). "Two of the most commonly used endogenous control genes for breast cancer gene expression studies are glyceraldehyde-3-phosphate dehydrogenase (GAPDH) and β-actin (ACTB) but their reliability in this context has not been demonstrated." (PMID 18042273, 2007). "However, a recent report showed that, in MDAMDB321 aggressive breast cancer cells, hypoxia (2% oxygen) enhance PAR1 expression on the basis of conventional qRT-PCR experiments using ACTB as HKG, gel analysis for transcript quantification, but no reported data regarding the choice of ACTB." (PMID 20179706, 2010).